ARID1A (AT-rich interaction domain 1A)
Diseases named in the same sentence as ARID1A in open-access papers (continued):
Sharing a sentence is not in itself a finding about the gene and the disease.
endometrial cancer (continued). "Although ARID1A alterations are most prominently described in ovarian and endometrial cancers, their identification in this skull-based lesion aligns with increasing evidence that epigenetic dysregulation may be a crucial driver of neoplastic transformation in plasmacytomas." (PMID 41378284, 2025). "Therefore, we investigated whether ARID1A negativity predicts the efficacy of ICIs in treating endometrial cancer." (PMID 38893118, 2024). "Therefore, we investigated whether ARID1A negativity predicts ICI effectiveness for endometrial cancer treatment." (PMID 38893118, 2024). "The identification of novel variants in genes such as ARID1A, BRIP1, MLH1, PIK3R1, and PTEN expands the understanding of the genetic basis of endometrial cancer, suggesting that a broader spectrum of mutations may contribute to the disease than previously recognized." (PMID 39296440, 2024). "Therefore, it is unclear whether ARID1A is useful as a biomarker for predicting response to ICI therapy in patients with endometrial cancer." (PMID 38893118, 2024). "However, a study of endometrial cancer found that ARID1A plays a role in epigenetic silencing (methylation) of the MLH1 gene, speculating that ARID1A mutations preceded MSI." (PMID 37366273, 2023). "Similarly, there is no clear association between ARID1A loss and prognosis in endometrial carcinoma." (PMID 38275587, 2023). "However, concurrent loss of ARID1A and ARID1B has also been detected in some cancers and in mice, dual deletion of Arid1a and Arid1b causes de-differentiation and promotes liver, squamous cell carcinoma, and endometrial cancers." (PMID 35323214, 2022). "In addition to ARID1A, it should be noted that CHD4 mutations leading to nucleosome remodeling defects are also frequent in endometrial cancer and may lead to de-repression of similar target genes." (PMID 36153585, 2022). "Intriguingly but noticeably, Arid1ad/d mice show aberrant active epithelial proliferation, but do not develop endometrial hyperplasia or endometrial cancer, suggesting that Arid1a loss alone may not be enough to cause the development of endometrial cancer." (PMID 34671561, 2021). "In addition, despite the mostly unknown genetic basis, in 14%–22% of uterine endometrial clear cell carcinoma (UCCC), a rare disease that accounts for <5% of all endometrial carcinomas, ARID1A expression is also found to be downregulated." (PMID 34671561, 2021). "ARID1A is a member of the SWI/SNF chromatin remodeling complex, and it is frequently mutated in endometrial adenocarcinoma, therefore it is conceivable how hTERT might be upregulated in the endometrial cancer with loss of ARID1A." (PMID 31157162, 2019). "Similarly, the homolog of ARID1A, ARID1B, is frequently mutated in endometrial cancer (9.7%) and in hepatocellular carcinoma (10.4%), but the abrogation mutation rate is <1%, which indicates that these are missense (i.e., silent) mutations which do not effect ARID1B expression." (PMID 25774356, 2014). "ARID1A, a key component of the SWI/SNF chromatin remodeling complex, is a tumor suppressor frequently inactivated in many cancer types, including endometrial cancer." (PMID 41800254, 2026). "Our study is the first report to investigate the relationship between ARID1A expression and immune-related molecules in MSS endometrial cancer." (PMID 38893118, 2024). "Patients with NSMP (as identified by an IHC-based on molecular classifier) endometrial cancer with mutant KRAS and wt ARID1A showed poor RFS compared with those with other KRAS/ARID1A statuses." (PMID 36797358, 2023). "For example, in low-grade endometrial cancer, the MAPK pathway is predominantly activated, and concomitantly, ARID1A is often inactivated." (PMID 38071325, 2023). "In a previous work by our group, we investigated the prognostic role of additional biomarkers (ARID1A and CTNNB1) in endometrial carcinoma in a subset of the analyzed cohort showing the relevance of an improved surrogate molecular classification." (PMID 37064027, 2023).
endometrial cancer (continued). "However, the prognostic capability of ARID1A loss has not been documented in endometrial cancer." (PMID 34257552, 2021). "The predictive value of ARID1A for predicting ICI effectiveness has not been reported for endometrial cancer." (PMID 38893118, 2024). "In this study, 24.5% of endometrial cancer samples were determined to be ARID1A-negative according to immunostaining, a result consistent with previous reports." (PMID 38893118, 2024). "In MSS endometrial carcinoma, no significant PD-L1 expression or immune cell infiltration were observed in the ARID1A-negative group." (PMID 38893118, 2024). "Furthermore, patients with NSMP endometrial cancer and combined mutant KRAS and wt ARID1A who underwent initial surgery have a poor prognosis." (PMID 36797358, 2023). "In the multivariate analysis performed using a Cox proportional hazards model, patients with endometrial cancer with mutant PTEN and ARID1A had a better RFS than those with wild-type PTEN and ARID1A (HR = 0.42, 95% CI = 0.25–0.69, P < 0.001; HR = 0.58, 95% CI = 0.35–0.97, P = 0.040, respectively)." (PMID 36797358, 2023). "MAPK and ARID1A have been observed to have a negative correlation in endometrial carcinomas based on proteomics datasets from The Cancer Genome Atlas (TCGA)." (PMID 38071325, 2023). "Most endometrial cancer cell lines do not express ESR1 and harbor ARID1A mutations as well as other cancer-driver mutations." (PMID 35326450, 2022). "The results of this study showed that knocking out the ARID1A gene, a tumor suppressor, could downregulate progesterone receptor B (PRB), enhance AKT phosphorylation, and attenuate MPA sensitivity in endometrial cancer cells." (PMID 35715750, 2022). "In endometrial cancer cell lines, the phosphorylation of several downstream targets such as AKT and PDK1 in the PI3K pathway is markedly upregulated, which supports the view that ARID1A is a new regulator in the PI3K pathway." (PMID 34671561, 2021). "As previously shown in endometrial cancers, increased pAKT was also found in tumors with ARID1A/BAF250a loss when both PIK3CA mutation or PTEN loss were absent." (PMID 24559118, 2014). "Thus, ARID1A is not suitable for use as a biomarker to predict response to ICI therapy among patients with endometrial cancer because there are few cases of MSI-high in patients with ARID1A-negative tumors." (PMID 38893118, 2024). "Our findings suggest that ARID1A negativity may not be a suitable biomarker for ICI efficacy in endometrial cancer." (PMID 38893118, 2024). "However, it must be noted that other relevant endometrial cancer related genes (e.g., AT‐rich interaction domain 1A, ARID1A) were not included in our gene panel, which represents a limitation in our study." (PMID 36373729, 2022).
endometrial cancer (continued). "Our study showed that the mutations commonly occurred in the ER negative subtype group, suggesting that inactivation of ARID1A might play important role in ER-mediated transcription in endometrial cancer." (PMID 30057548, 2018). "Although AT-rich interaction domain 1A (ARID1A) negativity has been proposed as a new biomarker for immune checkpoint inhibitors, there have been no reports on ARID1A biomarkers in endometrial cancer." (PMID 38893118, 2024). "The result was confirmed through proteomics database exploration, revealing negative correlations between ARID1A, DUSP4, and MAPK molecules in large published datasets of endometrial carcinomas." (PMID 38071325, 2023). "This suggests that concomitantly ARID1A negative staining and ß-Catenin nuclear and membrane/cytoplasm positive (n+m+) staining respectively ß-Catenin nuclear and membrane negative staining (n-m-) might play a role in tumor progression in type I endometrial cancer." (PMID 29451900, 2018). "ARID1A alterations were detected in 19% (6/32) of HGSOC and and 67% (6/9) of other OC cases; however, no tissue alterations were found in non-malignant tumours or the sole endometrial cancer case." (PMID 36982928, 2023).
endometriosis (137 papers, 2012 to 2026). The growth of functional endometrial tissue in anatomic sites outside the uterine body. "For example, one recent study found that 79% (19 out of 24) of women with endometriosis exhibited mutations in genes such as ARID1A, KRAS, and PIK3CA within the epithelial cells of the endometriotic lesions analyzed." (PMID 40227624, 2025). "Mutations in ARID1A have been observed in the two main neoplastic transformations associated with endometriosis." (PMID 41465243, 2025). "Another tumor suppressor gene implicated in endometriosis is ARID1A (AT-rich interaction domain-containing protein 1A)." (PMID 39859551, 2025). "Loss of ARID1A function is considered an early stage of malignant transformation of endometriosis, which can occur in CCOC and EC." (PMID 41465243, 2025). "A typical endometriosis is the putative precursor of ERONs, in which ARID1A mutations are already observed." (PMID 40076621, 2025). "Essential factors for the progression from endometriosis to endometriosis-associated ovarian cancer include somatic mutations in ARID1A, K-RAS, PTEN, and microsatellite instability." (PMID 40508002, 2025). "Evidence indicates that 79% (19/24) of patients with endometriosis have mutations in ARID1A, KRAS, and PIK3CA in the epithelial tissue of endometriotic lesions." (PMID 40860812, 2025). "OCCC is frequently linked to endometriosis and characterized by mutations in ARID1A and PIK3CA, hyperactivation of the PI3K/Akt/mTOR pathway, and overexpression of VEGF, HIF-1α, and IL-6." (PMID 41383608, 2025). "CCC is believed to originate from endometriosis, but ARID1A or PIK3CA mutations have been found in benign endometriosis and even in normal uterine endometrial glands." (PMID 40459063, 2025). "For instance, the loss of ARID1A, although rare, suggests aberrant signaling pathways in endometriosis." (PMID 40649777, 2025). "In endometriosis that develops in the ovary during a process similar to retrograde menstruation, a partial mutation in the ARID1A gene occurs." (PMID 41303820, 2025). "Significantly, endometriosis is the sole benign condition where a deficiency in ARID1A expression has been detected, even in situations where there is no indication of malignancy." (PMID 38610698, 2024). "The mutation of ARID1A has also been observed in endometriosis, with evidence suggesting that endometriotic lesions are precursors to the development of OCCC and EnOC, with disease progression driven by loss of this tumour suppressor." (PMID 39272926, 2024). "Should this be the case, it would suggest that at least in OCCC associated with endometriosis, the loss of ARID1A is an early event in the timeline of tumorigenesis." (PMID 39272926, 2024). "ARID1A mutation is present in endometriosis, and given that OCCC and EnOC are identified as EAOCs, this points to the involvement of abrogated SWI/SNF as an early driver of tumorigenesis." (PMID 39272926, 2024). "Somatic ARID1A mutations also occur in endometrioid ovarian cancer (EnOC), as well as in the chronic benign condition endometriosis, possibly as precursors to the development of the endometriosis-associated cancers OCCC and EnOC." (PMID 39272926, 2024). "Exome sequencing of lesions from deep infiltrating endometriosis shows somatic variants in oncogenic driver genes such as ARID1A, PIK3CA, KRAS, or PP2R1A." (PMID 38132375, 2023). "Results of molecular studies have highlighted the presence of ARID1A gene mutations in 46% of clear-cell and 30% of endometrioid ovarian cancers and in areas of endometriosis that are contiguous with these cancers." (PMID 38029403, 2023). "EOC and endometriosis share some molecular features, such as different mutations, for example, in ARID1A, PTEN, KRAS and PIK3CA." (PMID 38139300, 2023). "As recently reported for estrogen receptor-positive breast cancer, the role of mutations in the ARID1A gene leading to a modulation of estrogen receptor signaling can contribute to the pathogenesis of endometriosis." (PMID 37240796, 2023).
endometriosis (continued). "It is more likely to be endometrioid, emerging from endometriosis-associated cancer, with loss of ARID1A function." (PMID 36831656, 2023). "Based on their results, the loss of ARID1A acts as an initial trigger for the malignant transformation of endometriosis tissue and arises independently of the “atypical endometriosis” phenotype." (PMID 37627318, 2023). "Molecular profiling of the endometriosis-associated ovarian carcinomas, including ovarian endometrioid and clear-cell carcinomas, showed frequent loss-of-function mutations in ARID1A." (PMID 37621654, 2023). "Clear-cell and low-grade endometrioid epithelial OCs associated with endometriosis frequently harbor ARID1A mutations." (PMID 37109525, 2023). "In OCCC, ARID1A mutation is often found in contiguous endometriosis and is an early event in neoplastic transformation." (PMID 38275587, 2023). "Mutation of the ARID1A gene was demonstrated in atypical endometriosis originating from ovarian endometriomas and localized adjacent to ovarian CCOC and ENOC tumors." (PMID 36612107, 2022). "ARID1A is a tumor suppressor gene that is frequently mutated in endometriosis-related ovarian neoplasms, including clear cell and endometrioid carcinoma." (PMID 35621684, 2022). "This is also consistent with the fact that ARID1A mutations are frequently associated with endometriosis." (PMID 36082022, 2022). "ARID1A mutations and loss of expression are also observed in deeply invasive forms of endometriosis, which is characterized by ectopic spread of the endometrium." (PMID 36153585, 2022). "The frequent loss of function ARID1A mutations in cancers arising from endometriosis (endometrial tissue growth outside the uterus) makes SWI/SNF an attractive option for targeted therapy approaches." (PMID 36430148, 2022). "The component of clear cell carcinoma showed a nuclear positive reaction against PAX8 and napsin A, as well as a loss of ARID1A, suggesting typical endometriosis-derived clear cell carcinoma." (PMID 35327349, 2022). "ARID1A mutation phenotypically leading to decrease in protein BAF250a represents an initial genetic change of endometriosis overthrow." (PMID 35012617, 2022). "A significant number of SMBTs that exhibit loss of expression of ARID1A and their common association with endometriosis reveal that these tumors are closely related to endometrioid carcinomas." (PMID 35621684, 2022). "Among 24 SMBTs, loss of ARID1A expression in 8/24 (33%) cases and one case with loss of ARID1A expression in synchronous endometriosis were reported." (PMID 35621684, 2022). "This is also evident from the fact that endometriosis related ovarian tumors including seromucinous, clear cell and endometrioid tumors show ARID1A mutations with loss of ARID1A expression in a high proportion of cases." (PMID 33736662, 2021). "A large number of studies have also found that patients with endometriosis have many gene mutations, including mutations in ARID1A, PIK3CA, KRAS, FBXW7, MLH1, ERBB2, CTNNB1, and PPP2R1A." (PMID 34150634, 2021). "AT‐rich interaction domain 1A (ARID1A) is a 250 kD switch/sucrose non‐fermentable chromatin remodelling complex subunit with known tumour suppressor function and is associated with both endometriosis and orchestration of endometrial receptivity." (PMID 34586697, 2021). "On the other hand, the frequency of ARID1A mutation is clearly higher in EAOC compared to endometriosis and normal endometrium, indicating that ARID1A mutation plays an important role in oncogenesis." (PMID 33809880, 2021). "Whole-exome sequencing has explored that 79% of patients with deep-infiltrating endometriosis had some harboring oncogenic driver mutations, such as ARID1A, KRAS, PIK3CA, and PPP2R1A." (PMID 34444500, 2021).